MYC (MYC proto-oncogene, bHLH transcription factor)
Diseases named in the same sentence as MYC in open-access papers (continued):
Sharing a sentence is not in itself a finding about the gene and the disease.
lymphoma (continued). "Patients with lymphoma cells co-expressing MYC and BCL-2 have been shown to respond better to ABT-737 (a selective inhibitor of BCL-2, BCLxL, and BCLw), showing that BCL-2 has a critical role in DHL." (PMID 33216822, 2020). "We next analyzed the relevance of c-MYC in regulating miR-7e-5p expression in the progression of lymphoma." (PMID 33168041, 2020). "Immunohistochemistry showed positivity for Ki-67 (approximately 90%), BCL2 (approximately 80%) and MYC (approximately 70%) double-expressor lymphoma." (PMID 32664092, 2020). "It is quite pellucid that the interrelation between MYC and lncRNAs plays a critical role in blood cancers such as leukemia and lymphoma." (PMID 33134177, 2020). "Deregulation of c-MYC has been extensively investigated in many cancer types including leukemia and lymphoma but little is known about the expression and role of c-MYC in ATL lines and uncultured ATL cells." (PMID 32907612, 2020). "This synthetic lethal interaction led to decreased tumor growth in MYC-expressing lymphoma and hepatoblastoma in vivo models." (PMID 33322239, 2020). "In a panel of mouse MYC-driven lymphomas, tumor growth was dependent on MHC I expression that seemed to regulate innate immune surveillance." (PMID 32549409, 2020). "Many other genes are involved in the pathogenesis of lymphoma cross-talking with MYC, mainly through transcriptional regulation." (PMID 32549409, 2020). "In lymphoma cells, lncRNAs exist that can regulate the translation of the MYC specific mRNA in cooperation with the eukaryotic translation initiation factor 4E (eIF4E)." (PMID 33134177, 2020). "Given the essential role of MYC in DLBCL/HGBL pathogenesis and its association with relapse, different therapeutic strategies are being developed to target MYC-dependent lymphomas." (PMID 33260693, 2020). "In marked contrast, simultaneous overexpression of PIM1 and MYC dramatically accelerates MYC-induced lymphomagenesis, leading to formation of aggressive lymphomas in utero or around birth." (PMID 33054831, 2020). "The polycomb group transcription factor, BMI-1, was identified as an oncogene that cooperates with MYC in mouse lymphomas." (PMID 32759846, 2020). "S63845 treatment (25 mg/kg) led to a complete tumor regression at day 100 post-treatment in xenograft models of MM and a 70% cure rate in immune-competent Eμ-MYC mouse lymphomas, respectively." (PMID 33308268, 2020). "Of note, MYC recruited EZH2 to miR-26a promoter repressing miR-26a expression in aggressive lymphoma cell lines as well as primary lymphoma cells." (PMID 32549409, 2020). "Recent in vivo studies of Alisterib in MYC-overexpressing lymphoma xenografts demonstrated synthetic lethality by caspase-independent cell death and complete tumor regression when paired with chemotherapy cyclophosphamide." (PMID 33322239, 2020). "In Burkitt’s and AIDS-associated lymphomas, this region is frequently mutated, signifying that MYCBP2 suppresses MYC activity." (PMID 32085659, 2020). "Efficacy of novel CAR T cells targeting other antigens, such as CD22, CD30 and CD79b and innate immunity-mediated CAR NK cells on MYC overexpressing lymphomas are under investigation." (PMID 33092116, 2020). "Using genome editing in human and mouse MYC-driven lymphoma, the study demonstrates its pro-proliferative and anti-apoptotic activity in BL and identify its nuclear localization as an oncogenic event in germinal center B-cell derived lymphomagenesis." (PMID 32549409, 2020). "Several lymphoma derived MYC mutants, including P57S and T58A, have been previously shown to dramatically increase the half-life of MYC protein, and also confer increased transforming capacity." (PMID 31844144, 2020). "The concept of “glutamine addiction”, a phenomenon also described for MYC overexpressing lymphomas, indicates the increased demand for glutamine as a source of carbon and nitrogen in cancer cells." (PMID 33092116, 2020).
lymphoma (continued). "IHC analysis also helps define the double expressor DLBCL (c-MYC/BCL-2 overexpression, 25% of de-novo DLBCL cases), while FISH determines the double/triple hit lymphomas (genetic rearrangement of c-MYC/BCL-2 or BCL-6, 6-14% of de-novo DLBCL cases)." (PMID 32019190, 2020). "Here, we report that high expression of tribbles homologue 3 (TRIB3) positively correlates with elevated MYC expression in lymphoma specimens; TRIB3 deletion attenuates the initiation and progression of MYC-driven lymphoma by reducing MYC expression." (PMID 33298911, 2020). "In brief, malignant cells require elevated MYC levels to sustain the high proliferative rate of lymphoma cells." (PMID 31454887, 2019). "Recently, there is growing interest in the double expressor lymphomas (DELs), defined as co-expression of 2 oncogenes (MYC and BCL2) based on immunohistochemical staining." (PMID 31702637, 2019). "We found that GCN5 (KAT2A) mRNA is overexpressed in certain lymphomas, and especially in Burkitt lymphomas, which have high expression of MYC." (PMID 31645904, 2019). "Phosphorylation of GSK3β by AKT inactivates GSK3β kinase activity, and this inhibition is necessary for the fitness of MYC-driven lymphoma cells." (PMID 31645904, 2019). "There are feedback loops and feedforward loops, sustaining the oncogenic activity of ncRNAs: for instance, a feedback loop has been described in lymphoma between miR-17-92, MYC, the protein kinase Chk2 and hu antigen R (HUR)." (PMID 30987378, 2019). "Although MYC has been evaluated as a therapeutic target in other lymphomas, this strategy is yet to be explored in ENKTL." (PMID 30935402, 2019). "At the immunohistochemical level, it has been found that CD38 and CD44 can be used to distinguish between MYC-positive and MYC-negative lymphomas." (PMID 31484540, 2019). "We aimed to address the impact of the lymphoma type, EZH2 mutation status, as well as MYC, BCL2 and BCL6 translocations on the sensitivity of the lymphoma cell lines to DZNep-mediated apoptosis." (PMID 31419226, 2019). "STAT-mediated BATF3 expression is crucial for lymphoma cell survival and promotes MYC activity in classical Hodgkin lymphoma and anaplastic large cell lymphoma, and a new oncogenic axis is recognized in these lymphomas." (PMID 30987332, 2019). "Double/triple-hit lymphomas (DHL/THL) account for 5–10% of diffuse large B cell lymphoma (DLBCL) with rearrangement of MYC and BCL2 and/or BCL6 resulting in MYC overexpression." (PMID 31288832, 2019). "One clinical trial (NCT02992483) is currently investigating the preliminary activity of S63845 in refractory/relapsed multiple myeloma or lymphoma including MYC positive DLBCL." (PMID 30881917, 2019). "Combined treatment with JQ1 and PD-L1 antibodies showed synergistic responses in mice with MYC-driven lymphoma." (PMID 30906568, 2019). "Recently, the 2016 World Health Organization classification for lymphomas included a new category termed high grade B-cell lymphoma with translocations involving MYC and BCL-2 or BCL-6." (PMID 30704144, 2019). "Genes frequently mutated in BL are located in the BL-specific spot A (e.g. ID3, CCND3) and D (e.g. TCF3, SMARCA4, MYC) indicating their increased activity in BL and partly in intermediate lymphomas." (PMID 31039827, 2019). "Inhibition of the PI3K/AKT/mTORC1 axis and inhibition of MYC lead to a decreased viability of lymphoma cells and a decreased glycolytic activity seen by reduced glucose uptake, glucose metabolism, and glycolytic gene expression." (PMID 31454887, 2019). "Multiple hit lymphomas should be distinguished from “double expressor” DLBCLs in which MYC and BCL-2 genes are overexpressed at the protein level without the genetic rearrangements." (PMID 31115699, 2019). "Here, using a MYC-driven lymphoma model, we demonstrate that during malignant progression the rDNA chromatin converts to the open state, which is required for tumor cell survival." (PMID 30701204, 2019).
lymphoma (continued). "Five patients carried all the three rearrangements, so called “triple hit lymphoma” (THL – MYC+/BCL2+/BCL6+) and for survival analysis were considered among DHLs." (PMID 31976479, 2019). "Deregulated MYC is found in more than half of hematological malignancies, including T-cell and B-cell neoplasms, lymphomas and myeloid leukemia." (PMID 31196146, 2019). "Patients bearing a MYC+ lymphoma experience an aggressive clinical course and have a poor prognosis when treated with the standard regimen of rituximab, cyclophosphamide, doxorubicin, vincristine and prednisolone (R-CHOP)." (PMID 31028445, 2019). "In terms of further histological/molecular features of DLBCL, one patient with clonally related lymphoma was a double expressor of MYC and BCL2, and one presented with CD5+ aggressive lymphoma following an initially CD5− MALT lymphoma." (PMID 31124124, 2019). "Correlation between the lymphoma type, EZH2 mutation status, MYC, BCL2 and BCL6 rearrangements and DZNep sensitivity." (PMID 31419226, 2019). "“Double hit” lymphomas are characterized by the presence of both MYC and BCL-2 (or less commonly BCL-6) rearrangements, while “triple-hit” lymphomas demonstrate MYC, BCL-2, and BCL-6 rearrangements." (PMID 31115699, 2019). "The remaining 19 MYC rearranged patients, lacking an additional BCL2 or BCL6 translocation, were defined single hit lymphomas (SHL – MYC+/BCL2-/BCL6-)." (PMID 31976479, 2019). "L1 reportedly participates in genomic rearrangement in MYC-induced lymphoma, supporting the idea that L1 also contributes to MYC-mediated oncogenesis." (PMID 30717368, 2019). "The available genetic lymphoma models, mostly taking advantage of aberrant MYC or BCL2 overexpression in the B‐cell compartment, fail to capture the heterogeneity of the human disease." (PMID 31515941, 2019). "Progress is being made in the targeting of the regulation of MYC activity by BET inhibitors in the MYC-expressing murine lymphoma or DLBCL cell lines." (PMID 31288832, 2019). "Triple hit lymphomas harbor MYC, BCL-2, and BCL-6 rearrangements and have an aggressive clinical course and poor prognosis." (PMID 30718665, 2019). "The combination of BET inhibitors and BCL2 inhibitors decreased drug resistance in MYC-related lymphomas." (PMID 31403034, 2019). "The miRNA signature associated to MYC has been characterized in cellular models, in liver cancer, in neuroblastoma, in lymphomas known to overexpress MYC such as Burkitt’s lymphoma and diffuse large B-cell lymphomas and by computational methods." (PMID 30038718, 2018). "Hippuristanol inhibits the binding of mRNA to eIF4A and has been shown to reverse the resistance to chemotherapy and induce apoptosis in synergy with ABT-737 (BCL-2 inhibitor) in the Eμ-MYC lymphoma model." (PMID 29799508, 2018). "Typical of c-MYC-driven lymphomas, BLs proliferate rapidly but are also sensitive to apoptosis under conditions of stress." (PMID 28960205, 2018). "We had previously shown that Lyn kinase was upregulated in LMP2A/MYC and that targeting Lyn provided a therapeutic option for this lymphoma." (PMID 30135222, 2018). "Double-hit (DH) lymphomas, defined as lymphomas with MYC translocation combined with BCL-2 or BCL6 translocation, are among the most aggressive variants." (PMID 30287880, 2018). "In fact, BCL6 prevents MYC expression in the B-cells of the dark zone of the GC and adapts the cellular functions to the growth conditions of the lymphoma cells." (PMID 30038718, 2018). "Most Eμ‐MYC/Vav‐BFL1 mice also developed pre‐B lymphomas but a significant number (7 of 11 mice analysed) additionally developed CD19−B220+CD4+ progenitor cell lymphomas that have been described before for Eμ‐MYC/Eμ‐BCL2 mice." (PMID 29498802, 2018). "Stem/progenitor cell lymphomas also dominated in Eμ‐BCL2/Eμ‐MYC DT, Eμ‐Bclx/Eμ‐MYC DT and Vav‐Mcl1/Eμ‐MYC DT mice 29, 31, 32, while Vav‐BCL2/Eμ‐MYC DT mice developed IgM−CD19+CD43+ pro‐B cell tumours." (PMID 29498802, 2018).
lymphoma (continued). "We also evaluated the importance of BCL-W in human lymphomas known to be driven by or reliant on MYC expression, specifically Burkitt and DLBCL." (PMID 30671383, 2018). "Similar effects were also observed for lymphoma cell lines representative of aberrant MYC activity (CA-46) or constitutive Jak/STAT and NF-kB pathway activation (OCI-Ly3, L-428)." (PMID 29666362, 2018). "We selected lymphoma cell lines that express high levels of MYC due to amplifications (MM1S) or rearrangements (KMS11)." (PMID 29884215, 2018). "Of interest, an aberrant MYC expression in EBV-infect lymphoma cells has been seen, both in BL and other lymphomas." (PMID 29937761, 2018). "In our current study, we showed an increase in SYK phosphorylation in LMP2A-positive MYC-induced lymphoma and that targeting SYK with a novel SYK inhibitor, TAK-659, completely inhibited splenomegaly and tumorigenesis." (PMID 30135222, 2018). "The expression of MYC is tightly controlled during adult erythropoiesis, since misregulation of MYC expression leads to lymphoma and leukemia." (PMID 30186694, 2018). "“Double-hit” lymphoma (DHL) is a high-grade B-cell lymphoma that harbors concurrent MYC and BCL2 or BCL6 rearrangements." (PMID 30323893, 2018). "Herein, we describe a fully characterized lymphoma cell line harboring simultaneous MYC and BCL6 rearrangements, designated DH-My6, that is proved to be immunophenotypically and genetically consistent with a primary DHL tumor." (PMID 30323893, 2018). "Daily administration of Everolimus (5 mg/kg, 6 days per week) significantly improves Eμ-MYC-bearing mice survival (upon adoptive transfer of Eμ-MYC cells) and the median OS widely varies from one Eμ-MYC lymphoma to another." (PMID 30564554, 2018). "Here, we compared gene expression profiles of artificially induced overexpression of MYC in lymphomas of Eμ-Myc-transgenic mice with those of wild-type lymph node samples." (PMID 29741575, 2018). "The role of the combination of lenalidomide with standard R-CHOP21 in other subgroups of DLBCL with worse prognosis, such as MYC/BCL2 double expressors or double hit lymphomas remains to be defined, and further studies are ongoing." (PMID 30410035, 2018). "Enforced expression of repressed miRNAs diminished the tumorigenic potential of lymphoma cells indicating that MYC-repressed miRNAs function as tumor suppressor genes." (PMID 30038718, 2018). "So far, there have been various lymphoma cell lines that appear to have both MYC and BCL2 rearrangements." (PMID 30323893, 2018). "In fact, in this lymphoma type MYC+ cell counts ranged from 2% to 82%, allowing to test the miRNA signature on a wide dynamic range." (PMID 30038718, 2018). "BL is a typical highly proliferating and malignant MYC-driven lymphoma, while MCL is a CCND1-positive lymphoma with a heterogeneous clinical behaviour." (PMID 30038718, 2018). "A central role of glutaminolysis in resting and proliferating B-cells was shown for the MYC-inducible human B-cell line P493-6, which serves as a model of MYC-driven lymphoma or normal B-cells." (PMID 29666362, 2018). "The heterogeneity of Everolimus responses in vivo is likely related to the individual genetic alterations and the anti-apoptotic properties of each Eμ-MYC lymphoma." (PMID 30564554, 2018). "have described a transgenic mouse model in which atorvastatin reverses the development of MYC‐induced lymphomas in a dose‐dependent fashion." (PMID 29608241, 2018). "The small molecule BRD4 inhibitor JQ1 has been shown to downregulate the MYC transcriptional network and inhibit tumor growth of MYC-driven multiple myeloma, lymphoma, and neuroblastoma." (PMID 29880876, 2018).
lymphoma (continued). "One key gene that has been related both to carbohydrate and to lipid metabolic dysregulation in lymphomas is MYC." (PMID 29937761, 2018). "This has been studied in the Eμ-MYC lymphoma model, where MYC dramatically increases global protein synthesis, cell size, cell cycle entry, and lymphomatous transformation." (PMID 29799508, 2018). "In switchable models of MYC-induced lymphoma and osteosarcoma, the ability of MYC to induce ribosomal gene products and enhance protein translation correlates with its ability to sustain tumorigenesis." (PMID 29799508, 2018). "“Double-hit” lymphoma (DHL) represents a subset of B-cell malignancies characterized by the presence of MYC (8q24) rearrangement and concurrent BCL2 (18q21) or BCL6 (3q27) rearrangements." (PMID 30323893, 2018). "Second, we analyzed perturbation signatures of (i) mouse lymphomas with artificially induced MYC overexpression and (ii) knock-out experiments of NANOG, POU5F1 and SOX2 in human embryonic stem cells." (PMID 29741575, 2018). "Second, we analyzed perturbation signatures of artificially induced overexpression of MYC in lymphomas of Eμ-Myc-transgenic mice as well as knock-out experiments of NANOG, POU5F1 and SOX2 in human embryonic stem cells." (PMID 29741575, 2018). "In particular, BATF3 can dimerize with Jun in the MYC promoter and support the proliferation and survival of lymphoma cells." (PMID 29661228, 2018). "MYC overexpression can upregulate oncogenic miRNAs, such as the miR-17-92 cluster directly activated in lymphoma, and can also repress several suppressor miRNAs." (PMID 30237861, 2018). "These therapies are RNA-based (not miRNA-based); they do not knockdown or overexpress miRNAs but target oncogenes such as Bcl-2 (NCT00285103) in CLL, STAT3 (NCT01563302) in DLBCL and lymphoma, and MYC (NCT02314052) in HCC." (PMID 30443251, 2018). "In particular, it is important to determine if disruption of genes controlling disparate apoptotic and senescence pathways that can co-operate with MYC, when synthetically de-regulated are actually affected in spontaneously arising Eμ-Myc lymphomas." (PMID 28262675, 2017). "DLBCL, Burkitt’s and other lymphoma often display MYC rearrangements and to a lesser extent gene amplifications." (PMID 29050199, 2017). "In MYC-driven TSC2+/−Eμ-Myc lymphomas, DHX9 suppression had a straight lethal effect both ex vivo and in vivo." (PMID 28427210, 2017). "MYC/BCL2 lymphomas were described as neoplasms with a phenotype characteristic of germinal center B cells: they express BCL6 and CD10, and lack IRF4, a regulator of BCL6." (PMID 28375188, 2017). "MYC is relevant in several lymphomas, but little data indicate its relevance in mantle cell lymphoma (MCL)." (PMID 29057015, 2017). "MYC is a significant oncogene, and its deregulation has been shown to lead to the development of aggressive lymphomas." (PMID 28983465, 2017). "Dysregulation of c-MYC in B-cell lymphomas occurs either as a primary event in Burkitt lymphoma, or secondarily in aggressive lymphomas such as diffuse large B-cell lymphoma, plasmablastic lymphoma, mantle cell lymphoma, or double-hit lymphoma." (PMID 28379189, 2017). "Since the main prerequisites for the optimal management of lymphomas are accurate pathological diagnosis and the provision of predictive biomarkers, MYC became an important point of investigation due to its complex links with a large number of human genes." (PMID 28375188, 2017).